TCEAL4 (transcription elongation factor A like 4)
Description:
May be involved in transcriptional regulation.
Synonyms: NPD017; FLJ21174; WEX7
Tractability: PROTAC: ubiquitination databases record sites on it.
Gene: Protein-coding gene on chromosome X (103,576,231 to 103,590,165, forward strand). Ensembl gene ENSG00000133142.
Subcellular location: Nucleus
Gene Ontology:
Molecular function: protein binding
Cellular component: nucleus
Homologues: Orthologues: chimpanzee TCEAL4 (99% identical), macaque TCEAL4 (97% identical), dog TCEAL4 (68% identical), pig TCEAL2 (66% identical). Paralogues in human: TCEAL2 (82% identical), TCEAL3 (47% identical), TCEAL5 (47% identical), TCEAL6 (45% identical), TCEAL9 (18% identical), TCEAL8 (18% identical), TCEAL1 (17% identical), TCEAL7 (13% identical).
Diseases named in the same sentence as TCEAL4 in open-access papers:
TCEAL4 is named in the same sentence as 14 diseases in open-access papers, as found by Europe PMC text mining. Sharing a sentence is not in itself a finding about the gene and the disease. The quoted sentences say what the papers report.
anaplastic thyroid cancer (2 papers, 2006 to 2013). "In this study, we examined expression levels of TCEAL4 in anaplastic thyroid cancers as well as other types of thyroid cancers and normal thyroid tissue." (PMID 17076909, 2006). "Expression of TCEAL4 was down-regulated in anaplastic thyroid cancers as compared to either normal thyroid tissue or differentiated thyroid cancer tissue." (PMID 17076909, 2006). "We also investigated the expression of TCEAL4 in cell lines derived from 11 anaplastic thyroid cancers (ACLs) and five normal thyroid tissues by SQ-PCR and Q-PCR." (PMID 17076909, 2006).
gastric cancer (2 papers, 2006 to 2013). A primary or metastatic malignant neoplasm involving the stomach. "A real-time quantitative PCR was performed on normal gastricepithelial cell line GES1 and gastric cancer cell lines including AGS, MKN45, MGC803, SGC7901 and HGC27 to determine the mRNA levels of TCEAL1, TCEAL3, TCEAL4, TCEAL5, TCEAL7 and TCEAL8." (PMID 23372750, 2013). "The TCEAL7 expression level was significantly lower in the gastric cancer cell lines comparing with the levels of TCEAL1, TCEAL3, TCEAL4, TCEAL5 and TCEAL8." (PMID 23372750, 2013). "TCEAL4 expression was absent or under-expressed in 46 of 91 (51%) cell lines examined, namely hepatic cell carcinomas, gastric cancers, colon cancers, ACLs, ovarian cancers, cervical cancers, lung cancers, urinary bladder cancers, renal cell carcinomas and neuroblastomas." (PMID 17076909, 2006).
autism (1 paper, 2020). Persistent deficits in social interaction and communication and interaction as well as a markedly restricted repertoire of activity and interest as well as repetitive patterns of behavior. "Also, a small 252-kb duplication spanning BEX3, TCEAL4, TCEAL9, and RAB40A has been reported in a patient with autism (Decipher database, ID: 290829)." (PMID 33100228, 2020).
thyroid cancer (1 paper, 2006). "To assess whether the loss of expression of TCEAL4 was specific to ACLs, we examined TCEAL4 expression by SQ-PCR in 91 of cancer cell lines including differentiated thyroid cancers derived from papillary and follicular cancers." (PMID 17076909, 2006). "To investigate the role of TCEAL4 in ATC carcinogenesis, we examined expression levels of TCEAL4 in ACLs as well as in other types of thyroid cancers and normal human tissue." (PMID 17076909, 2006).
cancer (2 papers, 2006 to 2025). A tumor composed of atypical neoplastic, often pleomorphic cells that invade other tissues. "We successfully identify cancer-associated genes such as BRCA1, BRCA2, PALB2, and TCEAL4, all exhibiting the sought-after expression patterns." (PMID 40983914, 2025). "The detailed function of TCEAL4 has not been described nor has any association between this gene and human cancers been reported previously." (PMID 17076909, 2006). "To date, genetic alterations of TCEAL4 in human cancers have not been described." (PMID 17076909, 2006).
gynecological tumor (1 paper, 2017). "Genes that highly expressed in EAEMT compared with EA type cells were TCEAL4, BAG1, VAT1, and GPI which are known to be gynecological tumor markers." (PMID 29079795, 2017).
TCEAL4 also shares sentences with these, for which no sentence is quoted: cervical cancer (1 paper); colon cancers (1); follicular thyroid cancer (1); lung carcinoma (1); neuroblastoma (1); ovarian carcinoma (1); renal cell carcinoma (1); urinary bladder cancer (1).